EGFR (epidermal growth factor receptor)
Diseases named in the same sentence as EGFR in open-access papers (continued):
Sharing a sentence is not in itself a finding about the gene and the disease.
ovarian carcinoma (continued). "Poziotinib, a panhuman epidermal growth factor receptor, was reported to decrease sphere formation, viability/proliferation, and induced G1 cell-cycle arrest and apoptosis in ovarian cancer stem cells." (PMID 38534733, 2024). "Studies indicate the potential efficacy of EGFR inhibitors such as cetuximab or gefitinib in treating ovarian cancer by disrupting EGFR-mediated signaling pathways." (PMID 39194519, 2024). "Recently, a study has documented that the enhancement of chemosensitivity in ovarian cancer to cisplatin can be increased by EGFR blockade." (PMID 38202856, 2024). "Our study aimed to analyze the cellular mechanism of dacomitinib, a pan-epidermal growth factor receptor (EGFR) inhibitor, which resensitized paclitaxel and induced cell cytotoxicity in paclitaxel-resistant ovarian cancer SKOV3-TR cells." (PMID 38202856, 2024). "EGFR is an important molecule for targeting cancer cells and it is frequently overexpressed by human ovarian cancers and in many other carcinomas." (PMID 39261715, 2024). "In ovarian cancer, EGFR expression and activation correlate with tumor progression and poor prognosis." (PMID 39194519, 2024). "In ovarian cancer, LINC01089 is downregulated by M2-like tumor-associated macrophages (TAMs) secreting EGF, which activates the EGFR-ERK signaling pathway." (PMID 39334363, 2024). "SYK positively regulates EGFR and has been shown to be involved in EGFR signaling in squamous cells and ovarian carcinoma, where it contributes to paclitaxel and lapatinib resistance." (PMID 37760847, 2023). "Increased synthesis of ErbB members including epidermal growth factor receptor EGFR, ErbB2, ErbB3, and ErbB4, which are associated with the development of solid tumours, such as tumours associated with breast, colorectal and ovarian cancer." (PMID 39935547, 2023). "Kaplan–Meier survival analysis spotlighted AKT1, JUN, EGFR, and VEGFA as potential diagnostic and prognostic biomarkers for ovarian cancer." (PMID 37964873, 2023). "It is strongly suggested that overexpressed RUNX1 regulate the abnormal proliferation of ovarian cancer cells through the EGFR-AKT-STAT3 axis and RUNX1 work as a potential target for ovarian cancer treatment." (PMID 38057816, 2023). "To elucidate the molecular pathways by which ST6GAL1 regulates EGFR activation, we performed mechanistic studies using the three ovarian cancer cell lines, OV4, OVCAR-3, and OVCAR-5." (PMID 37660914, 2023). "In ovarian cancer, CD24 and EGFR have been characterized in exosomes and proposed as potential biomarkers for ovarian cancer." (PMID 36675253, 2023). "It was previously shown that epidermal growth factor receptor (EGFR) is overexpressed in 75% of ovarian cancers." (PMID 37511995, 2023). "These patients included an ovarian cancer patient with KRAS G12D and EGFR G724S mutations with SD (- 9%) for 7 months and a salivary gland cancer patient with EGFR amplification by IHC with SD (+ 3%) for 5 months." (PMID 37314501, 2023). "Thereafter, a number of regulated proteins in the downstream signaling pathway of EGFR were identified by examining the mechanism through which MICALL2 induced MMP9 transcription in ovarian cancer cells." (PMID 38203692, 2023). "Abundant EGFR expression has been shown to render mouse ovary carcinoma cell insensitivity to radiation." (PMID 37177859, 2023). "In the MAPK pathway, the use of EGFR inhibitors to ovarian cancer has seen limited success in clinical trials, possibly attributed to the scarcity of EGFR mutations in ovarian cancer which the inhibitor targets." (PMID 37612696, 2023). "Another research indicated that ovarian cancer cell migration was induced by betacellulin through EGFR-MEK/ERK signaling." (PMID 36655117, 2023).
ovarian carcinoma (continued). "designed CAR with a glucocorticoid-induced TNFR-related protein (GITR) co-stimulatory domain and recorded that EGFR-GITR-CD3 CAR-T cells were cytotoxic against EGFR+ pancreatic and ovarian cancer cells with higher levels of IFN-γ." (PMID 37457699, 2023). "MEK/ERK1/2 was activated by FAM83D protein and can up-regulate the expression of MMP2 and activate EGFR through a ligand-dependent mechanism, thereby leading to the invasion and metastasis of ovarian cancer cells." (PMID 37476189, 2023). "The overexpression of CXCR2 in tumor cells can lead to ovarian cancer progression by enhancing NF-κB activation via EGFR-transactivated Akt signaling, thereby upregulating the expression of pro-inflammatory chemokines." (PMID 37765018, 2023). "Preclinical studies on an ovarian cancer mouse model clearly showed that an oral dose of PEITC significantly suppressed ovarian cancer tumor growth seemingly by targeting inhibition of the EGFR-Akt pathway." (PMID 37190316, 2023). "E-cadherin was detected in early-stage ovarian carcinoma and functioned to increase cell survival and proliferation by inducing EGFR dimerization and activation in a ligand-independent manner." (PMID 37760996, 2023). "Specifically, TAM in ovarian cancer activates EGFR through secreted EGF and up-regulates VEGF/VEGFR signals in peripheral tumor cells, supporting tumor cell proliferation and migration." (PMID 37005667, 2023). "Phase II trials of gefitinib in ovarian cancer reported low toxicity and promising clinical results by inhibiting the phosphorylation of EGFR." (PMID 36768961, 2023). "For example, macrophage migration inhibitory factor (MIF) can inhibit the activation of EGFR, while EGFR can promote the growth of various tumors and has been identified as a key therapeutic target of epithelial ovarian cancer." (PMID 37719881, 2023). "miR-7 inhibits tumor metastasis and reverses the epithelial–mesenchymal transition through AKT/ERK1/2 inactivation by targeting EGFR in epithelial ovarian cancer." (PMID 36012357, 2022). "One previous study revealed that PDK1 silencing induces apoptosis and overcomes cisplatin resistance in ovarian cancer-resistant cells by downregulating the EGFR activation pathway." (PMID 36474273, 2022). "Pharmaceutical development strategies have largely shifted to combinations of TKIs with chemotherapeutics, targeted therapies, and/or immune modulators for drug-resistant cancers, especially chemotherapy-resistant ovarian cancer and EGFR TKI-resistant NSCLC." (PMID 35820889, 2022). "This indicates that μ receptor plays an important role in EGFR activation-induced by fentanyl in ovarian cancer cells." (PMID 35999506, 2022). "These exosomes are captured by ovarian cancer cells, and miR-7 decreases these cells’ metastasis by inhibiting the EGFR/AKT/ERK1/2 signaling pathway." (PMID 35550636, 2022). "EGFR-depleted ovarian cancer cells were then treated with fentanyl, followed by migration and proliferation analysis." (PMID 35999506, 2022). "The evidence suggested that berberine consumed EGFR and ERBB2 in ovarian cancer cells and inhibited the activation of EGFR and ERBB2 downstream targets cyclin D1, MMPs, and VEGF via the EGFR-ERBB2/PI3K/Akt signaling pathway." (PMID 35889396, 2022). "The level of p-AKT was decreased after treatment of an EGFR antagonist (JMR-132) in ovarian cancers." (PMID 35846125, 2022). "Various cancer biomarkers associated with ovarian cancers have been considered for the design of tumor-targeting agents, including the folate receptor, VEGF, EGFR, HER2, epCAM, PSMA, and αvβ3 integrin." (PMID 35625796, 2022). "Samudio‐Ruiz and Hudson previously showed that EGFR activation in ovarian cancer leads to a pattern of global methylation, reversible upon treatment with a hypomethylating agent." (PMID 35224804, 2022). "EGFR depletion abolishes the effects of fentanyl in ovarian cancer, confirming that EGFR is the target of fentanyl." (PMID 35999506, 2022).
ovarian carcinoma (continued). "These were bound to the antibody Cetuximab which is directed against EGFR (epidermal growth factor receptor), a common target in ovarian cancer cells." (PMID 35251021, 2022). "A common family of RTKs often observed as overexpressed in ovarian cancer is the epidermal growth factor receptor (EGFR) or ErbB family." (PMID 36140214, 2022). "TAMs release epidermal growth factor (EGF) in ovarian cancer, and directly activate the EGFR-ERK pathway." (PMID 35565348, 2022). "The epidermal growth factor receptor (EGFR) has been proposed as a promising therapeutic target in ovarian cancer, as up to 70% of ovarian tumors are EGFR-positive." (PMID 37304006, 2022). "Fentanyl treatment resulted in significantly increased phosphorylation of EGFR by 3.4-fold but not placental derived growth factor receptor (PDGFR), demonstrating the specific activation of EGFR by fentanyl in ovarian cancer cells." (PMID 35999506, 2022). "HB-EGF, probably released via the actions of enzymes a disintegrin and metalloproteinase 17 (ADAM17) or cathepsin B, induces the transactivation of EGFR, which leads to increased proliferation of epithelial ovarian cancer cells." (PMID 35216283, 2022). "In ovarian carcinoma cells in 3D collagen, EGFR and MT1-MMP colocalize with caveolae prior to activation and stimulation with EGF disrupts their association and leads to MT1-MMP internalization." (PMID 35819726, 2022). "The down regulation of GALNT14, which is up-regulated in ovarian cancer, inhibits the activity of mTOR pathway through O-glycosylation of EGFR, thereby inhibiting ferroptosis in ovarian cancer cells." (PMID 35784729, 2022). "In ovarian cancer, EGFR, which promotes tumor proliferation and migration, was reported to be a direct and functional target of miR-7." (PMID 36012357, 2022). "A previous study reported that EGF and BDNF promote metastasis and proliferation of ovarian cancer cells by transactivating TrkB and EGFR, respectively." (PMID 35898394, 2022). "Upregulation of GALNT2 and GALNT6 resulted in enhanced migration and invasion of oral and ovarian cancer cells, in part by increasing O-glycosylation and activation of the EGFR." (PMID 35028012, 2022). "Aberrant epidermal growth factor receptor (EGFR) is found in ~ 60% of ovarian cancers and is correlated with poor prognosis, drug resistance, metastasis and low survival rate." (PMID 35999506, 2022). "Fentanyl activates ovarian cancer via simulating EGFR signaling pathways in an opioid μ receptor-dependent manner." (PMID 35999506, 2022). "Given the importance of EGFR activation in ovarian cancer, we firstly investigated the EGFR signalling using immunoblotting approach in fentanyl-treated ovarian cancer cells." (PMID 35999506, 2022). "TGF-α secreted by stromal fibroblasts in turn promotes peritoneal metastasis of ovarian cancer through epidermal growth factor receptor (EGFR) signaling." (PMID 36503378, 2022). "Mouse ovarian cancer models treated with erlotinib (an EGFR inhibitor) noted reduced spheroid formation and metastatic progression, underlining an important function of TAMs in disease progression." (PMID 35565348, 2022). "As EGFR is overexpressed in 70% of ovarian cancers and is correlated with chemoresistance and a worse prognosis, the authors looked further into the role of MEK1." (PMID 36499737, 2022). "LncRNA MEG3 can be a promising biomarker for ovarian cancer diagnosis and treatment by modifying the epithelial-mesenchymal transsition of ovarian cancer cells through sponging miR-219a-5p and modulating EGFR." (PMID 35109842, 2022). "EGFR overexpression has been reported during ovarian cancer progression and correlates with a poor prognosis." (PMID 37304006, 2022). "In another study, C225 antibody targeting EGFR combined with benzoporphyrin derivate monoacid A (BPD)-PDT showed efficacy in an OVCAR5 model of ovarian cancer." (PMID 35158887, 2022).
ovarian carcinoma (continued). "Both EGFR and HER2 increases are also common phenomena in ovarian cancer and are associated with adverse clinical outcomes." (PMID 35269825, 2022). "EGFR is a key factor in driving EMT, and earlier research has shown that sialylation of EGFR by ST6Gal-I encourages both basal and ligand-dependent EGFR activation in pancreatic and ovarian cancer cells." (PMID 36547200, 2022). "It has been recently proposed that EGFR motivates the chemoresistance of epithelial ovarian cancer cells via GFR/MEKK pathways." (PMID 35739532, 2022). "A significant finding of our work, in agreement with the previous reports, is that the molecular mechanism of fentanyl on ovarian cancer cells is via activating EGFR." (PMID 35999506, 2022). "In future, more comprehensive research needs to be done to unravel the protein and gene molecules along the complex EGFR signalling pathway in ovarian cancer to identify biomarkers that can accurately gauge the sensitivity of EGFR-targeted therapeutic agents." (PMID 33800113, 2021). "In ovarian cancer cells, EGFR activation promotes SLUG transcription by inducing the expression of the transcription factor Egr-1, which directly binds to the SLUG promoter." (PMID 35127732, 2021). "In a similar study, gefitinib-mediated cell death was suppressed in ovarian cancer cells by augmented activation of epidermal growth factor receptor (EGFR) which positively correlated with upregulation of ST6Gal-I expression." (PMID 34577144, 2021). "Accordingly, targeting EGFR protein has been suggested as a promising strategy for targeted cancer therapy, since the EGFR is commonly overexpressed in many human cancers, including non-small cell lung, head, breast, bladder and ovarian carcinoma." (PMID 33921332, 2021). "Examples include human epidermal growth factor receptors EGFR (HER1) and ERBB2 (HER2) whose overexpression in head and neck, ovarian, cervical, bladder and esophageal cancer (EGFR), or breast and ovarian cancer (HER2) is associated with poor prognosis." (PMID 34201655, 2021). "Another study reports that an overexpression of HtrA1 in ovarian cancer cells inhibits epidermal growth factor receptor (EGFR) activation, leading to lower levels of AKT/MAPK phosphorylation and a significant rise in cell death." (PMID 34639128, 2021). "Although this study investigates PA imaging of PAtrace for FRα+ SKOV3 ovarian cancer, this technology can be applied to a variety of cell receptors (e.g., epidermal growth factor receptor) and cancer cells that are accessible with PA imaging." (PMID 34518530, 2021). "As an example, the combination of methotrexate (targets folate synthesis) and erlotinib (EGFR inhibitor) in UWB1289 (BRCA1-mutant ovarian carcinoma) cells is antagonistically efficacious and potent by MuSyC, but synergistic by Loewe." (PMID 34326325, 2021). "We have previously demonstrated co-immunoprecipitation of Gal3, MUC16, and Epidermal Growth Factor receptor (EGFR) protein and showed co-localization of the three proteins in ovarian cancer explants and human ovarian cancer sections." (PMID 33580170, 2021). "miR-7-loaded cationic liposomes inhibit epidermal growth factor receptor (EGFR) and suppress the spread of ovarian cancer." (PMID 34831320, 2021). "Previously, LPA has been shown to activate EGFR for ovarian cancer cell invasion, suggesting transactivation between GPCR and RTK." (PMID 34065317, 2021). "On the other hand, TGFα secreted by stromal fibroblasts in turn promotes peritoneal metastasis of ovarian cancer, through epidermal growth factor receptor (EGFR) signalling." (PMID 33671588, 2021). "They showed that treatment with AREG upregulates sprouty RTK signaling antagonist 2 (SPRY2) expression by activating the EGFR-mediated ERK1/2 signaling pathway in ovarian cancer." (PMID 33922533, 2021). "Previous research confirmed that treatment with gefitinib (EGFR inhibitor) led to high STAT3 phosphorylation in ovarian cancer." (PMID 34369236, 2021).
ovarian carcinoma (continued). "Overall, overexpression of EGFR in ovarian cancer patients is correlated with advanced-stage disease, high tumor grades, and increased metastatic potential." (PMID 34503128, 2021). "The knockdown of ST6Gal I in ovarian cancer cells reduced EGFR activation and increased sensitivity to gefitinib-induced cell death." (PMID 34069424, 2021). "EGFR is an important driver of EMT, and our prior studies demonstrated that ST6Gal-I-mediated sialylation of EGFR promotes both basal and ligand-dependent EGFR activation in pancreatic and ovarian cancer cells." (PMID 33148698, 2021). "EGFR is overexpressed in 70% of malignant ovarian tumours and 85% of salivary adenoid cystic carcinomas, leading to increased mRNA levels of SLUG." (PMID 35127732, 2021). "To explore the roles of EGFR and IL-6-STAT3 in ovarian cancer, we first comprehensively explored the prognostic significance of EGFR and IL-6-STAT3 pathway in patients with ovarian carcinoma using the Kaplan–Meier plotter (KM plotter)." (PMID 34369236, 2021). "We have previously shown that physiologically-relevant flow-induced shear stress (3 dyne/cm2, 2 μl/min) induces a post-translational upregulation and activation of the EGFR in perfusion models of 3D ovarian cancer." (PMID 32231055, 2020). "It has been recently shown that increased cell sialylation induced lower response of GC cells to the anti-ErbB2 monocolonal antibody trastuzumab as well as reduced response of ovarian cancer cells to the EGFR TKI gefitinib." (PMID 31979110, 2020). "Of interest, an enhanced and detrimental autophagy was similarly observed following an ALKBH5 silencing/miR-7-5p increase and subsequent downregulation of the EGFR/Akt/mTOR axis in epithelial ovarian cancer cells." (PMID 33066037, 2020). "About 11% of ovarian tumors have ErbB2 amplification, whereas EGFR overexpression is found in up to 28% and amplified in up to 20% of ovarian cancers." (PMID 32754300, 2020). "Phosphorylation of EGFR at Y1173 was also increased in ovarian cancer cells under flow compared to static culture." (PMID 32231055, 2020). "Inhibition of the EGFR/AKT signaling pathway promotes ovarian cancer cell differentiation via regulating TSA." (PMID 32897242, 2020). "PIC–Nal–IRI is highly selective against EGFR-overexpressing epithelial ovarian cancer cells with 2- to 6-fold less accumulation in low EGFR expressing cells." (PMID 31898555, 2020). "We have previously reported that expression of the EGFR, a poor prognostic factor of ovarian cancer, is post-translationally upregulated under flow-induced shear stress." (PMID 32231055, 2020). "We have previously shown a post-translational upregulation and activation of the epidermal growth factor receptor (EGFR) in a 3D perfusion model for ovarian cancer." (PMID 32231055, 2020). "For example, in a mouse model of ovarian cancer, tumor cell-derived TNFα induced omental fibroblasts to produce TGFα, which in turn stimulated ovarian cancer EGFR and accelerated metastatic potential." (PMID 33069212, 2020). "It was previously shown that flow-induced mechanical stress mediates a post-translational increase in the expression of EGFR in ovarian cancer cells." (PMID 32231055, 2020). "CAF-derived TGF-α promotes the metastatic colonization of ovarian cancer cells via the activation of the Akt, epidermal growth factor receptor (EGFR), and extracellular signal-regulated kinase (ERK)-1/2 signaling pathways." (PMID 32546182, 2020). "The study also found that LPA stimulated COX-2 expression and cell movement through the LPA2-Gαi-Src-epidermal growth factor receptor (EGFR)-ERK signaling cascade in ovarian cancer cells." (PMID 32284748, 2020). "Following intraperitoneal injection in mice bearing OVCAR-5 ovarian cancer micrometases, these immunoconjugates were shown to bind the EGFR-overexpressing cancer cells." (PMID 32899137, 2020).